TNF (tumor necrosis factor)
Diseases named in the same sentence as TNF in open-access papers (continued):
Sharing a sentence is not in itself a finding about the gene and the disease.
infection (continued). "Patients treated with TNF inhibitors (TNFi; OR = 0.160, 95% CI 0.099–0.260, P < 0.001) and tocilizumab (OR 0.147, 95% CI 0.053–0.408, P < 0.001) had reduced odds of infection." (PMID 35770002, 2022). "C-reactive protein (CRP), an acute-phase inflammatory protein is primarily synthesized and stored in hepatocytes, and released in response to infection and inflammation, primarily with the stimulation of IL-6 followed by IL-1 and tumor necrosis alpha (TNF-α)." (PMID 35683357, 2022). "During the infection of M. tuberculosis, lncRNAs were considered to regulate TNF expression in macrophages to impact the replication of bacteria." (PMID 36494502, 2022). "Considering the mouse response to infection by C. neoformans, the most highly upregulated transcripts after 6 h of infection were involved in recognition, uptake, and phagocytosis, including IL-18 and TNF." (PMID 36497155, 2022). "As the infection time of F. nucleatum increased, the expression levels of TNF-α and IL-1β also increased." (PMID 35765030, 2022). "The microorganism strongly triggered the secretion of the tested pro-inflammatory cyto- and chemokines IL-6, IL-8, and TNF-alpha, determined at 24 h post-infection." (PMID 36519178, 2022). "Especially, TNFAIP3 belong to tumor necrosis factor were influenced during FAdV-4 infection process and play vital roles in the inflammatory response." (PMID 35774982, 2022). "This resulted in a roughly twofold increase in TNF and several‐fold increase in IL‐6 release by MDMs after infection with TIGR4Δply compared to TIGR4." (PMID 35835695, 2022). "Among different pro-inflammatory cytokines analyzed in this study, TNF-α, a predominant cytokine released during inflammation and/or infection, is most often believed to act as an inducer of sperm phosphatidylserine translocation or DNA fragmentation." (PMID 35955814, 2022). "Next, in an independent experiment, we analyzed the supernatants from the same cell lines infected with 100 VP/cell collected at day 1, 2 and 3 after infection, for virally produced human IL-2 and TNFα." (PMID 35355980, 2022). "We then measured the expression of inflammatory cytokines such as IL-6, IL-8, and TNF-α in BMECs after infection with M. bovis under different strains and at different MOIs." (PMID 35464378, 2022). "SARS-CoV-2-spike-specific T cells are characterized by significant interleukin-2 (IL-2) production, with tumor necrosis factor (TNF) also produced early after natural infection." (PMID 36075216, 2022). "It was noted that mice inoculated with 140Gy irradiated parasites displayed a higher standard deviation when measuring Th1 type responses, mediated by IFNγ and TNFα which are essential when controlling the first peak of infection." (PMID 35634275, 2022). "This systematic review aims to compare the incidence of infections and skin manifestations after anti-TNF-α dose de-escalation with standard dosing." (PMID 35625771, 2022). "Tumor Necrosis Factor alpha (TNF-α) is an acute phase reactant in early systemic inflammation which recruits leukocytes to the site of infection and/or tissue damage." (PMID 35919644, 2022). "CD4+ TNF expression was significantly lower in persistent infection compared to active infection (p=0.0058) as was CD4+ EGR2 (p=0.020)." (PMID 36439147, 2022). "All strains of Mmuc upregulated the proinflammatory cytokines TNF-α, IL-6, and IL-12p40 upon infection, and their levels increased in an MOI-dependent manner." (PMID 35269631, 2022). "Innate decreased expression of IFN γ and tumor necrosis factor-alpha (TNF-α) in neonates and infants is postulated to be associated with increased susceptibility to infection." (PMID 36533244, 2022). "Accumulating data have demonstrated that fish TNFα genes are upregulated during the early stages of infection." (PMID 36560667, 2022). "The levels of IL-2, IL-6, and TNF-α increased more than 80-fold upon infection with the ∆katG mutant." (PMID 35438052, 2022).
infection (continued). "During inflammation/infection processes, increased levels of TNFα lead to uncontrolled astrocyte glutamate release, altered PP‐GC circuit processing and, ultimately, impaired contextual memory performance." (PMID 34904753, 2022). "On the one hand, TNFα plays a vital role in resolving infection and tissue repair through the signal transduction pathway." (PMID 35621957, 2022). "Even though Th1 cells through IFNγ and TNFα are required for host control of mycobacteria, their enhanced activity in anti-PD-1 blockade seems to worsen infection in some cases." (PMID 35432383, 2022). "The results of qRT-PCR showed that, in 5XFAD mice, the expression levels of TNF-α and IL-1β mRNA are elevated after infection with F. nucleatum." (PMID 35813949, 2022). "Ratios of IL-10 to TNFα and IL-10 to INFγ show a persistent anti-inflammatory cytokine environment during the chronic stage of infection." (PMID 36420267, 2022). "On the fourth day post-infection increased levels of TNF cytokine in brain cortical tissue, adhesion of leukocytes and the minimal presence of edema restricted to a focal area in the brain have been observed." (PMID 36505414, 2022). "Here, we observed that infection of epithelial cells with P. aeruginosa leads to the induction of genes associated with MAPK, IL-17, and TNF signaling pathways." (PMID 35508983, 2022). "Next, we evaluated the presence of soluble polypeptides for IFNγ, IL-1β, IL-4, IL-6, IL-8, IL-10, CXCL10, and TNFα in serum of animals following infections with Att-S74-T3Bo and Vir-S74-T3Bo." (PMID 36466866, 2022). "Twenty hours after infection, macrophages infected with the ΔbepD and ΔbepA-I mutants showed elevated TNF-α secretion compared to wild-type infected cells." (PMID 35910598, 2022). "Severe infections with SARS-CoV-2 are strongly associated with a cytokine storm characterized by high levels of inflammatory cytokines, including IL-6 and TNF-α, in the plasma of patients." (PMID 35409421, 2022). "Correspondingly, BCG ΔPPE36 infection led to the increased inflammatory cytokines (TNF-α, IL-6, and IL-1β) and the reduced lung bacterial loads." (PMID 35237255, 2022). "Other mechanisms of Plasmodium-infection induced HIV replication include the secretion of TNF-α that can act directly stimulate HIV replication." (PMID 36504775, 2022). "TNF-α is a pro-inflammatory factor and is secreted in response to cellular infection, inflammation, and environmental stress." (PMID 36407538, 2022). "M. tuberculosis infection is known to induce production of type I IFNs that can lead to suppression of other cytokines, including TNF-α, which are critical for controlling infection." (PMID 35924849, 2022). "Cytokines can be proinflammatory, such as IL-1β, IL-6, and TNF-α, and alert other immune cells to the infection, or they can be anti-inflammatory." (PMID 36558734, 2022). "Type I IFN attenuates the ability to warn off infection through reducing T-cell activation and decreasing important defense cytokines such as TNF-α and IL12." (PMID 36286068, 2022). "Compared to wild-type infections, cells infected with the ΔvirD4 mutant secreted significantly higher levels of TNF-α secretion." (PMID 35910598, 2022). "It produces proinflammatory cytokines and chemokines like interleukin (IL)-12 and tumor necrosis factor alpha (TNFα), induces further inflammation and IFNγ release, and attracts neutrophils, natural killer (NK) cells, and lymphocytes to the site of infection." (PMID 35432348, 2022). "The RANTES, IFN-α, MIP-1-α, and IFN-γ mRNA levels during reinfection were similar to the levels in the primary infection group; the levels of IL-6, IP-10, TNF-α, and IL-1-β were increased during reinfection but were lower than those during primary infection." (PMID 35893674, 2022). "In line with the in vitro data, 4 hr after infection BALF TNF levels were higher in animals infected with TIGR4Δply compared to TIGR4." (PMID 35835695, 2022).
infection (continued). "It is widely accepted that CD4+ T helper 1 (Th1) cells, which express the cytokines interferon-gamma (IFN-γ) and tumor-necrosis-factor (TNF), play a major role during infection with Mtb." (PMID 36139450, 2022). "TNF-α and IL-1β, two potent pro-inflammatory cytokines, play an important role in the early stage of the inflammatory response to the infection of influenza virus." (PMID 35764970, 2022). "Consistent with the findings from ILN, these results indicated that VLPs containing both AMA1 and MIC induced CD4+ T cell responses, and lessened the production of inflammatory cytokines IFN-γ and TNF-α in the spleen upon P. berghei challenge infection." (PMID 35468726, 2022). "To examine IL-6, IL-1β, IFN-γ, and TNF-α mRNA expression in mice lungs following infection with EHV-8, we inoculated BALB/c mice with EHV-8 and analyzed them by qPCR." (PMID 36230234, 2022). "Remarkably, the knockdown of Nbeal2 significantly promoted the production of IL-1α, IP-10, IL-6, CCL-4 and TNF-α at 24 h post-infection in P815 cells infected with H1N1 virus and H5N1 virus." (PMID 35215885, 2022). "Through repeated comparison, we found that several cytokines, including IL-1 (interleukin-1), IL-6 (interleukin-6), TNF-α (tumor necrosis factor-α), and IFN-γ (interferon-γ), always coexist and are critical to CRS caused by infection or immunotherapy." (PMID 35431655, 2022). "Radiation-induced changes in normal tissues are triggered with an acute inflammatory response with release of cytokines, tumor necrosis factor (TNF), growth factors, etc., which causes vascular endothelial damage and infection –like symptoms at first." (PMID 35744008, 2022). "Our group recently demonstrated that IL-32γ in transgenic mice infected with Leishmania infantum was able to induce a Th1/IFN-γ/TNF-α and Th17/IL-17 profiles, which lead to increase of NO production to protect against the infection." (PMID 35097133, 2022). "Inflammation- and infection-associated genes TIMP2 (tissue inhibitor of metalloproteinase 2) (rs2277698), COL4A3 (collagen type IV alpha 3 chain) (rs1882435) and TNF variants were explored in more than one targeted study." (PMID 35379367, 2022). "Signaling delivered through TNFR2/mTNF-α ensures intercellular communication and it is linked to acute Mtb infection controlling, whereas long-term infection control additionally requires soluble TNF." (PMID 35163035, 2022). "The results revealed that the immunized mice with Montanide adjuvant and later infected with E. canis had significantly higher TNF gene expression (p < 0.01) than other mice groups 14 days after infection." (PMID 36006302, 2022). "Overall, TNF inhibitors pose significant risks in infection, with TNF-R mimics posing relatively lower risks compared to α-TNF mAb’s." (PMID 36159650, 2022). "The IAV single-infection group showed a rapid increase in the levels of TNF-α, IL-1α, IL-6, and IFN-β from 2 dpi to 7 dpi." (PMID 35107382, 2022). "The viability of E44 on HBMECs surface and intracellular of each group and IL-6 and TNF-α were used as indicators of invasion, adhesion, and inflammation after E44 infection." (PMID 36289622, 2022). "A meta-analysis that included 71 clinical trials showed 40% of serious infections were attributed to TNF inhibitor use." (PMID 36430392, 2022). "We next activated CAP using non-invasive ultrasound-based neuromodulation and demonstrate that further stimulated CAP suppression of the TNF response was also time- or immune status-dependent during infection." (PMID 35784337, 2022). "The infection caused by APEC in this study led to a significant increase in the expression of IL-1β, IL-6 and TNF-α mRNA in mice brains." (PMID 35900973, 2022). "TNF-a was equally triggered in both cases, however, the pro-inflammatory genes IL-8 and IL-1b transcribed upon TNF-a induction seem to have a higher expression following infection with the mutant isolate." (PMID 35215144, 2022).
infection (continued). "As an inflammatory protein, CCL4 coordinates the immune response to infection or inflammation and promotes the expression of pro-inflammatory cytokines including TNF—α, IL-6 and IL-1 β in activated macrophages and fibroblasts during inflammation." (PMID 35287569, 2022). "TNF-α is a proinflammatory cytokine involved in early recruitment and activation of the innate immune system in response to infection." (PMID 36159650, 2022). "Accordingly, and in agreement with a drop in infectivity, alterations in IL-8 and TNF-α cytokine transcription levels were measured together with a change in the number of mRNA copies for the viral M-gene 24 h post infection with influenza viruses." (PMID 35414213, 2022). "In order to determine this, we pretreated HeLa cells with TNF-α to activate NF-κB signaling, followed by an infection with HAdV-5." (PMID 36439101, 2022). "A high TNF to IL‐10 ratio has been reversely correlated to infection outcome in severe burn patients." (PMID 35285058, 2022). "The results indicated that MRSA and MSSA treatment of MAC-T cells increased the protein expression of TNF-α, IL-6, cleavage–Caspase3, Phospho-p65, and PrP, and then the protein expression of Bcl-2 appeared to decrease slightly with the duration of infection." (PMID 35812882, 2022). "In cGAS knockdown cells, we observed that, although viral RNA levels were unchanged, there was a significant decrease in TNF and IL-6 mRNA transcript levels following infection." (PMID 35022513, 2022). "The cytokines MCP-1, IFN-γ, TNF-α, IL-10, IL-12, andIL-6 were measured in culture supernatants 4- and 48-hours post-infection." (PMID 35910486, 2022). "At 20°C, the expression of Ciita, NFYB, NFYC, CALR, Canx and TNF reached the peak at 24 hpi, which was significantly higher and earlier compared to 10°C infection group." (PMID 35197977, 2022). "IL-1β is a chemoattractant for neutrophils in zebrafish, and TNF-α is one of the early immune genes expressed at an early stage of infection in fish and has a key role in regulating inflammation." (PMID 35563763, 2022). "Consistent with the transcriptional analysis, the level of TNF and IL-6 protein upregulation induced by infection was also significantly decreased in VS-X4 treated cells compared to controls cells." (PMID 35022513, 2022). "Cardiac toll-like receptors (TLRs) recognize general infection patterns and release proinflammatory cytokines such as interleukin-1β (IL-1β), IL-6, IL-18, TNF-α, and type I and type II interferons (IFNs)." (PMID 35479306, 2022). "We found that the highest AUC was LPS-induced TNFα production capacity (0.82), which has been repeatedly shown in many different patient populations to be a highly predictive marker of infection." (PMID 35958579, 2022). "The frequency of CD11b- KCs producing TNF-α, even after infection, was very low, while the frequency of cells producing IL-10 increased after infection." (PMID 35720410, 2022). "In a meta-analysis focusing on patients with RA, psoriatic arthritis, and ankylosing spondylitis, 30.8% of the anti-TNF-α users had at least one infection during follow-up." (PMID 35625771, 2022). "The TNF production was significantly increased at 24 hours post-infection in β-B.1.351 (South Africa) infected-MDM compared to uninfected MDM and Wuhan-infected MDM (p=0.0279)." (PMID 36601113, 2022). "In the acute phase of an infection, plasma levels of the inflammatory cytokines TNF-α, IL-1β and IL-6 increase, followed by enhanced secretion of acute-phase proteins that contribute to antimicrobial defence." (PMID 36510325, 2022). "A recent study demonstrated that IFN-γ and tumor necrosis factor-alpha (TNF-α) levels increased steadily in infected D2.129P2 (B6)-Nfκb1 wild-type mice, peaking at day 10 post-infection (p.i.)and declining to uninfected levels by day 20 p.i.." (PMID 35740465, 2022). "During infection of murine J774 macrophages, AC are readily engulfed and trigger a strong tumor necrosis factor-alpha (TNFα) response." (PMID 35783442, 2022).
infection (continued). "BALF levels of the proinflammatory cytokines IL-1β, IL-6, and TNF were similar in both mouse strains at 6 h after infection." (PMID 35269409, 2022). "The results showed that the levels of IL-4, IFN-γ, and TNF-α increased, and IL-10 decreased after infection with T. gondii." (PMID 36245502, 2022). "Choriodecidual infection with E. coli resulted in a progressive increase in TNF-α secretion to culture media in both compartments." (PMID 35328414, 2022). "Multiple studies observed increased levels of TNF-α during infection with various species of Legionella." (PMID 36159650, 2022). "One of the definite roles of CD4+ T cells in anti-TB immunity is to evolve into Th1 effector cells and produce IFN-γ and TNF-α to directly activate macrophages to control infection or kill MTB-infected macrophages." (PMID 36363564, 2022). "Only one article included information about the disappearance of infections after anti-TNF-α de-escalation." (PMID 35625771, 2022). "Other inflammatory cytokines, such as IL-4, IFN-γ and TNF-α, were also increased in comparison to control animals during the acute phase of infection." (PMID 35337002, 2022). "When macrophages trace an infection, TNF-α is released, which attracts other components of the immune system and assists in the immune response." (PMID 36355934, 2022). "We found that various immune pathways, such as those involving ILs, TNF, TLRs, cytokines, apoptosis, phagocytosis or metabolism, were significantly correlated with pathogen infection." (PMID 35565570, 2022). "This was contrary to expectation given that ablation of TNF with antibody treatment successful protected mice from PccAS-induced abortion following infection at E0.5." (PMID 35312688, 2022). "In contrast, co-pretreatment of TNFα with BGNAc largely rescued the ability of HCMV to initiate infection." (PMID 35834576, 2022). "TNF-α is a major inflammatory factor in the early stages of infection and has characteristics including earlier release and quicker recovery." (PMID 35887790, 2022). "Both IFN-γ and TNF are crucial to the control of Mtb burden during infection in preclinical animal models and human patients." (PMID 35320930, 2022). "Among others, we identified HGF, TWEAK, MMPs and TNFα as proteins that still remain enhanced after the infection phase of the disease." (PMID 36405747, 2022). "In the acute infection, the robust Th1 immune response, characterized by production of proinflammatory cytokines, as interferon-gamma (IFNγ) and tumor necrosis factor (TNF) is required for an efficient antiparasitic response." (PMID 35572567, 2022). "Mice in the CoHo-PBS group significantly reduced the mRNA expression levels of pro-inflammatory cytokines (IL-1β, IL-6, and TNF-α) compared with the SiHo-PBS group after infection." (PMID 35123452, 2022). "TNF-α (≥10 pg/mL) detected in infections by 75% of isolates, IL-6 (≥80 pg/mL) by 30% of isolates and low levels of NO (≥0.01μM) in almost all infections." (PMID 35531337, 2022). "Compared with the control, the expression levels of TNF-α (P < 0.01), IL-1β (P < 0.001) and IL-6 (P < 0.001) were significantly increased at 1 week after infection." (PMID 36171756, 2022). "MCs are an important first line of defense against various infectious agents due to the presence of TNF-α which recruit further neutrophils to the targeted site of infection and modulate both natural and acquired immune responses." (PMID 36619389, 2022). "Four dietary FPE concentrations were able to prevent the increase in splenic TNF-α, IL-8, and IL-1β expression levels elicited by infection." (PMID 34973140, 2022). "After infection with S. japonicum, KO rats also developed a strong pro-inflammatory response, with high production of TNF-α, IL-6, and IL-1β at all time points post-infection which reached a peak at 7 weeks post-infection." (PMID 35584107, 2022).